PRR35 (proline rich 35)
Synonyms: C16orf11; LA16c-366D1.2
Tractability: No criterion of Open Targets' tractability assessment is met for any kind of drug.
Gene: Protein-coding gene on chromosome 16 (559,688 to 565,532, forward strand). Ensembl gene ENSG00000161992.
Subcellular location (Human Protein Atlas): Nucleoli; Cytokinetic bridge; Cytosol
Gene Ontology:
Molecular function: protein binding
Genetic constraint (gnomAD): Loss-of-function variants: 15 observed, 13.34 expected, observed/expected ratio (o/e) 1.12, 90% interval 0.75 to 1.7. The synonymous counts are far from expectation, so gnomAD's model fits this gene poorly and the ratio says little. Missense variants: 832 observed, 638.08 expected, observed/expected ratio (o/e) 1.3, 90% interval 1.23 to 1.38. Synonymous variants: 425 observed, 307.15 expected, observed/expected ratio (o/e) 1.38, 90% interval 1.28 to 1.5.
Homologues: Orthologues: chimpanzee PRR35 (98% identical), macaque PRR35 (91% identical), mouse Prr35 (67% identical), rat Prr35 (67% identical), dog PRR35 (67% identical), pig PRR35 (66% identical), rabbit PRR35 (64% identical), tropical clawed frog prr35 (32% identical), zebrafish prr35 (30% identical). Paralogues in human: ZNF750 (19% identical), NHLRC4 (4% identical).
Diseases named in the same sentence as PRR35 in open-access papers:
PRR35 is named in the same sentence as 1 disease in open-access papers, as found by Europe PMC text mining. Sharing a sentence is not in itself a finding about the gene and the disease.
PRR35 shares sentences with these, for which no sentence is quoted: infection (1 paper).